CD36 (CD36 molecule (CD36 blood group))
Diseases named in the same sentence as CD36 in open-access papers (continued):
Sharing a sentence is not in itself a finding about the gene and the disease.
tumor (continued). "Studies in mouse models and human samples have shown that CD36 expression increases in tumor-infiltrating CD8+ T cells, dampening their function." (PMID 39402302, 2024). "CD36 is expressed in tumor cells, microvascular endothelial cells, stromal cells, and immune cells in tumor tissues." (PMID 38276607, 2024). "Within the tumor microenvironment, CD36-mediated fatty acid uptake by tumor-infiltrating CD8+ T cells leads to lipid peroxidation and ferroptosis." (PMID 38778030, 2024). "Meanwhile, immune cells in the tumor microenvironment overexpress CD36 and undergo metabolic reprogramming." (PMID 38276607, 2024). "The pathways responsible for CD36-dependent suppressive effects of macrophages in the TME have not been elucidated; however, there has been extensive study of the role of CD36 in the suppression of T cell anti-tumor responses." (PMID 39742252, 2024). "This lipid acquisition, facilitated through CD36, not only fuels the macrophages but also triggers their tumor-promoting activities." (PMID 39090094, 2024). "When coupled with anti-PD-1 therapy, CD36 inhibitors had greater anti-tumor effects than when used alone." (PMID 38302980, 2024). "Conversely, miR-3180 acts as a tumor suppressor by targeting CD36, thereby inhibiting both DNL and exogenous FA uptake and hindering HCC growth and metastasis." (PMID 38833109, 2024). "TSP-1 exerts its anti-tumorigenic activity by inducing the same apoptotic signaling cascade downstream from CD36 in tumor cells." (PMID 39627379, 2024). "High expressions of CD36 in tumor cells triggers FA uptake and lipid accumulation, promoting rapid tumor growth and initiating metastasis." (PMID 38276607, 2024). "This increase in CD36 expression facilitated enhanced uptake of unsaturated fatty acids by the tumor cells." (PMID 39399493, 2024). "The overexpression of CD36 on tumor and immune cells implicates tumor progression and manifests poor clinical outcomes in many cancers." (PMID 39062552, 2024). "More importantly, we showed that CD36 protein levels in tumor tissues of NSCLC patients were much higher than those in adjacent non-cancerous tissues." (PMID 38319449, 2024). "Another study showed that the number of TITRs in CD36−/− Treg mice was decreased, the anti-tumor activity of tumor-infiltrating lymphocytes was enhanced, and tumor growth was inhibited." (PMID 38807592, 2024). "Omental adipocytes reprogram tumor metabolism by upregulating CD36 in OvCa cells, thereby promoting tumor cell invasion and migration." (PMID 38276607, 2024). "TAMs uptake increased amounts of lipids from tumor cells by upregulating the expression of the scavenger receptor CD36." (PMID 39596288, 2024). "CD36 also plays a role in the tumor microenvironment, mediating FA uptake by CD8+ T cells and inducing lipid peroxidation and ferroptosis." (PMID 39857243, 2024). "This lipid metabolism is driven by the overexpression of enzymes in cancer cells for lipid uptake, such as CD36, and transcription factors for lipid oxidation enzymes or lipid synthesis by the tumor cells themselves." (PMID 39119332, 2024). "An analysis of the tumor microenvironment indicated that CD36 and MYD88 were significantly positively correlated with several microenvironment scores, suggesting their role in promoting the formation of an immune-supportive environment." (PMID 38919626, 2024). "In tumor microvasculature, CD36 binds to thrombospondin-1 (TSP-1), mediating endothelial cell apoptosis within tumor vasculature." (PMID 39640883, 2024). "The presence of cholesterol in the TME was shown to increase CD36 expression by CD8+ tumor-infiltrating lymphocytes in human cancer, and this led to increased lipid uptake, accumulation, and peroxidation." (PMID 39742252, 2024). "Futhermore, Gclc-OE CD8+ T cells exhibited reduced ferroptosis at the tumor site, along with decreased CD36 expression." (PMID 38360744, 2024).
tumor (continued). "Genetic ablation of CD36 in Treg cells suppressed tumor growth accompanied by enhancement of antitumor activity in tumor-infiltrating lymphocytes, and a decrease in intratumoral Treg cells without disrupting immune homeostasis." (PMID 39470474, 2024). "We assessed the effects of sulfosuccinimidyl oleate sodium (SSO), a CD36 inhibitor, on the proliferation apoptosis and alteration in tumor cell surface expression levels of immune accessory molecules in vitro." (PMID 39273384, 2024). "CD36 mediate increased Treg lipid metabolism in tumor cells, which increases Treg mitochondrial adaptability to changes in the TME and systemic metabolic demands." (PMID 38302980, 2024). "For example, CD36 mediates the uptake of fatty acids by tumor infiltrating CD8+ T cells in the tumor microenvironment, while increased expression of CD36 can induce lipid peroxidation and ferroptosis in CD8+ T cells, thereby inhibiting anti-tumor immunity." (PMID 39210921, 2024). "Human primary adipocyte coculture increased CD36 protein levels in tumor cells; furthermore, tumor cells that express high levels of the fatty acid receptor CD36 and lipid metabolism genes are unique in their ability to initiate metastasis." (PMID 38276607, 2024). "TSP-1 has also been shown to directly kill tumor cells via binding to CD36, resulting in apoptosis, as well as enhancing macrophage killing of tumor cells via binding to CD478–10." (PMID 38773224, 2024). "In conclusion, T cells in the tumor microenvironment are dysfunctional due to the regulation of CD36, which leads to immune suppression and promotes tumor development." (PMID 38276607, 2024). "Genetic ablation of CD36 reduces the presence of Tregs within the tumor and enhances the anti-tumor activity of other immune cells." (PMID 39678512, 2024). "Elevated cholesterol levels in the tumor microenvironment upregulate CD36 expression in tumor-infiltrating CD8+ T cells, inducing lipid peroxidation and ferroptosis, thereby impairing their effector function." (PMID 39402302, 2024). "In this review, we have highlighted the most relevant research of the past decade investigating the role of CD36 in treatment resistance in various neoplasms, either solid or haematological." (PMID 38370376, 2024). "Out of these 70 patients, 50 patients (71%) had high levels of CD36, 15 patients (24%) had medium levels and 3 patients (4%) had low levels in their tumor cells." (PMID 39627379, 2024). "In this case, inhibiting CD36 expression or preventing ferroptosis of CD8+ T cells can effectively restore anti-tumor activity." (PMID 39210921, 2024). "Our study, using PLA technology, found a significant interaction between CD47 and VEGFR, CD36, potentially impacting angiogenesis and cell metabolism within the tumor microenvironment, promoting tumor cell survival and proliferation." (PMID 39652550, 2024). "It seems that CD36 expression affects the metabolism of tumor cells by reducing glucose oxidation and promoting a higher uptake and storage of lipids from the diet, rather than activating the synthesis of in-house lipids." (PMID 38276607, 2024). "In a tumor microenvironment rich in PUFAs, CD36 facilitates uptake of PUFAs by tumor-infiltrating CD8+ T cells, which, in turn, promotes lipid peroxidation and ferroptosis." (PMID 38193763, 2024). "Recently, the functional role of CD36 in tumor immunity has generated much interest, particularly in immune evasion in cancer." (PMID 39273384, 2024). "Both cholesterol and fatty acids amplify the expression of the fatty acid translocase CD36 in tumor-infiltrating CD8+ T cells." (PMID 38217037, 2024). "CD36 allows the uptake of lipids from the extracellular microenvironment by cells and promotes ATP production, which stimulates tumor progression and metastasis." (PMID 39103344, 2024). "Out of 20 evaluable patients who provided biopsies, 16 patients (80%) had high CD36 levels in the tumor cells, and 4 patients (20%) had medium CD36 levels in the tumor cells." (PMID 39627379, 2024).
tumor (continued). "Better anti-tumor effects are obtained when CD8 + T cells with the CD36 gene deletion are combined with an anti-PD-1 antibody." (PMID 38302980, 2024). "The complexity of the tumor microenvironment presents a challenge to isolate specific signals that upregulate CD36 expression and stimulate immunosuppressive properties." (PMID 39742252, 2024). "Several studies have shown that CD36 is enormously elevated in tumor cells that are cocultured with adipocytes, which means that the expression of CD36 in tumor cells is sensitive to the concentration of fatty acids." (PMID 38276607, 2024). "All such cells express CD36 in tumor tissues; multiple studies have shown that CD36 contributes to the progression of many different cancers." (PMID 39062552, 2024). "FAs produced by de novo fatty acid synthesis via fatty acid synthase (FASN) or by the exogenous uptake of lipids from the TME (e.g., through the scavenger receptor CD36) fuel rapid tumor cell growth." (PMID 39667305, 2024). "Cholesterol and lactic acid, as well as oxidized phospholipids, were shown to lead to CD36-dependent CD8+ tumor-infiltrating lymphocyte dysfunction." (PMID 39742252, 2024). "CD36 on CD8+ tumor infiltrating lymphocytes (TILs) contributes to T cell dysfunction by facilitating the uptake of oxidized low-density lipoproteins (OxLDL) into T cells." (PMID 38414027, 2024). "Taken together, these results indicate that pitavastatin-mediated reduction in tumor progression is partly dependent on CD36 expression and lipid levels." (PMID 38319449, 2024). "Apolipoprotein C-II regulates lipid metabolism, and its interaction with CD36 promotes tumour progression via PI3K/AKT/mTOR signalling, which regulates the EMT process." (PMID 38974022, 2024). "Recent studies have revealed that the CD36 expressed by various tumor cells particularly affects tumor growth and metastasis." (PMID 39273384, 2024). "Metastatic Lewis lung carcinoma cells injected intraperitoneally into the spleen resulted in fewer metastatic nodules, overall decreased tumor area, reduced tumor proliferation and blood vessel number in CD36 KO mice compared to controls." (PMID 39742252, 2024). "Previous studies have revealed that CD36 inhibition enhances T cell immune responses and dendritic cell function in the tumor-bearing hosts of various types of cancers." (PMID 39273384, 2024). "A recent study has shown that CD36 induces lipid peroxidation and ferroptosis through its involvement in fatty acid uptake by tumor-infiltrating CD8+ T cells in the tumor microenvironment." (PMID 38218337, 2024). "Several anti-CD36 antibodies on the market today have been shown to work as CD36 inhibitors to stop tumor progression." (PMID 38276607, 2024). "The CD36-expressing tumor cell population represents a metastatic-prone subgroup of tumor cells, so SARIFA positivity combined with the assessment of tumor budding gives a new perspective to evaluate the potential of metastasis development." (PMID 39335115, 2024). "Consistent with in vitro results, we found that the reduction effect of pitavastatin on p-AKT and p-mTOR expressions in tumor tissues of CD36−/− mice was less than that in WT mice." (PMID 38319449, 2024). "CD8+ tumor‐infiltrating lymphocytes upregulate CD36 expression to promote oxidized low‐density lipoprotein uptake and reduce downstream T‐cell function due to increased peroxide levels in tumor cells." (PMID 39584783, 2024). "Strategically targeting CD36 amplifies the infiltration capacity and anti-tumor response of CD8+ T cells." (PMID 38217037, 2024). "Tumor-promoting macrophages express a high level of CD36, accumulate lipids, and use FAO for energy instead of glycolysis." (PMID 39062552, 2024). "Previous studies have shown that CD36 promotes tumor formation, metastasis, and treatment resistance through various molecular mechanisms." (PMID 39062552, 2024).
tumor (continued). "We elucidate a novel mechanism of ferroptosis in tumor-infiltrating T cells: cystine deprivation leads to glutamate accumulation, subsequently exacerbating CD36-mediated lipid peroxides production." (PMID 38360744, 2024). "A number of studies have shown that the targeting of lipid metabolism enzymes, such as FASN and CD36, restored the anti-tumor effect of CD8 + T cells and enhanced the effect of immunotherapy." (PMID 38302980, 2024). "In liver metastases, M2 macrophages engulf tumor cell-derived long-chain fatty acids via CD36 and enhance tumor-promoting activities." (PMID 38216787, 2024). "CD36 expression has been repeatedly presented as an unfavorable prognostic factor for various tumor types, such as ovarian and colon cancer 3,15,16." (PMID 38370376, 2024). "Our TMA data supports that tumor cells of patients with late stage disease express high levels of CD36 and CD47." (PMID 39627379, 2024). "Through CD36, the lipid-enriched vesicles are selectively taken up by macrophages, providing a fuel source for their metabolism and initiating tumor-promoting activities." (PMID 38276607, 2024). "There is a high expression level of CD36 in tumor cells, and its expression in metastatic foci is often more significant than that in the primary tumor site." (PMID 39744129, 2024). "In the tumor microenvironment (TME), immune cells upregulate CD36 to promote lipid uptake and suppress anti-tumor immunity." (PMID 39062552, 2024). "Our study highlights the significance of CD36 in promoting the development of a premetastatic niche in tumor-draining LN or SLN." (PMID 39062552, 2024). "Evidence shows that the overexpression of CD36 in TAMs increases their ability to take up lipids, which human and mouse tumor tissue macrophages are known to be rich in, and that TAMs can gain energy through FAO, which promotes protumor TAM phenotypes." (PMID 38276607, 2024). "The fatty acid receptor CD36 is expressed on various malignant cells and is suggested to contribute to tumor progression." (PMID 39273384, 2024). "Previous research has highlighted the role of STAT3 in facilitating lipid transport via CD36, thus supplying ample energy for tumor cell proliferation and migration." (PMID 38495496, 2024). "Targeting CD36+ on tumour-infiltrating lymphocytes leads to an enhanced CD8+ T cell effector function in melanoma models." (PMID 38610991, 2024). "On the one hand, the high expression of CD36 in tumor cells triggers fatty acid uptake and lipid accumulation, which helps promote rapid tumor growth and initiate metastasis." (PMID 38276607, 2024). "Further study revealed that cell proliferation and tumor progression were increased in cell overexpression CD36 while being reduced by CD36 inhibition, indicating that CD36 is a central regulator for NSCLC progression." (PMID 38319449, 2024). "Our previous study also revealed that CD36 was abundantly expressed by OSCCs and involved in the proliferation and migration of the tumor cells, whereas little is known about the role of CD36 in the host immune responses in OSCCs." (PMID 39273384, 2024). "Fatty acids (FAs) are efficiently transported from the TME to tumor cells by surface transporters in BC cells, such as CD36, fatty acid translocase (FAT) and fatty acid transporter protein (FATP)." (PMID 36765683, 2023). "We generated subcutaneous xenograft models to confirm the tumor-promoted function of CD36 in HFD-fed nude mice." (PMID 37612265, 2023). "According to other recent studies, cancer progression and metastasis are also promoted by the enhanced FFAs uptake and FFAs oxidation induced by the overexpression of CD36 in tumor cells." (PMID 37760840, 2023). "CD36 participates in tumor maintenance through its expression in intratumoral Treg cells by CD36-dependent metabolic adaptation and also participates in inflammation and sterile inflammation via TLR 4 and 6 activations." (PMID 37284503, 2023).
tumor (continued). "For instance, intratumoral Tregs are shown to alter their lipid metabolism to increase their survival via the CD36- PPAR-β axis for metabolic adaptation to the tumor microenvironment by enhancing fatty acid transport and mitochondrial fitness." (PMID 37205182, 2023). "The present study seeks to illuminate further the significance of CD36 repression in developing a tumor-supportive stroma." (PMID 37816052, 2023). "Oleic acid induced the activation of Src kinase and the downstream ERK1/2 pathway in a CD36-dependent manner, and the overexpression of CD36 in HeLa cells aggravated tumor growth and invasion in xenograft mice." (PMID 37056351, 2023). "Due to its varied function in tumor biology, CD36 has rapidly become an appealing therapeutic target in cancer." (PMID 37893423, 2023). "Atorvastatin can be used as an effective adjuvant drug targeting CD36 and preventing tumor metastasis." (PMID 37978381, 2023). "In liver metastasis mouse models, CD36 was upregulated in tumor-infiltrating TAMs, and CD36 knockout resulted in decreased lipid accumulation in TAMs." (PMID 37700339, 2023). "Fatty acid (FA) uptake and lipid metabolism are essential cellular processes to promote tumorigenesis and tumor progression, and CD36 is involved in this process." (PMID 37612265, 2023). "Nevertheless, these studies demonstrate the multifaceted roles CD36 plays in establishing immunosuppressive TMEs and shed light on the potential for remodeling the tumor immune milieu with anti-CD36 therapies." (PMID 37371076, 2023). "High CD36 levels are associated with enhanced EMT, tumor differentiation and lymph node metastasis through synergistic interactions with TGF-β." (PMID 37056351, 2023). "It was also recently described that CD36 plays a central role in cancer cell metastasis and that genetically or pharmacologically inhibiting CD36 can perturb tumor growth and metastasis across several cancer types." (PMID 37371076, 2023). "In recent years, CD36 has quickly emerged as an attractive therapeutic target in cancer due to its multifaceted role in tumor biology." (PMID 37371076, 2023). "Exogenous AA uptake via CD36 was required for ferroptosis in tumor-infiltrating CD8+ T cells and resulted in the loss of anti-tumor immunity." (PMID 37612411, 2023). "The scavenger receptor CD36 was reported to be highly expressed on tumor-infiltrating CD8+ T cells, but the clinical role remains obscure." (PMID 37085798, 2023). "CD36, a transmembrane glycoprotein receptor, is expressed in tumor, stromal, and immune cells and plays a significant role in regulating cell adhesion, immune response, metastasis, and angiogenesis in tumors." (PMID 38025525, 2023). "CD36 has diverse effects, including anti-tumor and tumor-promoting (such as CRC tumorigenesis) activities." (PMID 38186579, 2023). "CD36 inhibitors hinder tumor development, specifically metastasis and angiogenesis in the TME 238 and have shown synergistic effects in combination with the FASN inhibitors and anti-PD-1 therapy." (PMID 37064872, 2023). "Targeting the PI3K-AKT pathway significantly inhibited CD36+ myoepithelial cell-derived tumour spheres and the growth of PA organoids." (PMID 37679344, 2023). "Though we cannot ignore that CD36-mediated FA uptake promotes the FAs metabolism to provide energy for tumor cell proliferation and metastasis, it is more likely that CD36 can induce signal transduction in cells as a cell membrane protein." (PMID 37612265, 2023). "Targeting intratumoral lipid droplet formation or genetic deletion of CD36 curbs the pro-tumoral function of TAMs and suppresses tumor progression." (PMID 37740232, 2023). "The sum of the scores for these genes was higher than 5 or lower than −5 except for BCKDHA and CD36 in liver metastasis; therefore, in the particular tumour sample, these genes were considered to be inappropriate for normalization of the number of gene copies." (PMID 37686184, 2023).